PGR (progesterone receptor)
Diseases named in the same sentence as PGR in open-access papers (continued):
Sharing a sentence is not in itself a finding about the gene and the disease.
breast cancer (continued). "In early breast cancer (BC), five conventional biomarkers—estrogen receptor (ER), progesterone receptor (PgR), human epidermal growth factor receptor 2 (HER2), Ki67, and Nottingham histologic grade (NHG)—are used to determine prognosis and treatment." (PMID 32913985, 2018). "The production of sex hormone antagonists and their success in the treatment of patients with ERα+ and PgR+ breast carcinomas and AR+ prostate carcinomas have also suggested the investigation of the expression of these receptors in other tumors including SGTs." (PMID 29385707, 2018). "More interestingly, elevated FoxM1 expression predicted poor survival in breast cancer patients, especially in the ER (+), progesterone receptor (PR) (+) subgroups and BC patients received adjuvant chemotherapy only or treated with tamoxifen only." (PMID 29416660, 2018). "Breast carcinoma is a heterogenous disease classified into subtypes according to the expression of biological markers, such as estrogen receptor (ER), progesterone receptor (PR) and epidermal growth factor receptor 2 (HER2)." (PMID 30384831, 2018). "Breast cancers are divided into different subtypes depending on the expression of hormone receptors, including estrogen receptor (ER), progesterone receptor (PR), and epidermal growth factor receptor 2 (HER2 or erbB2)." (PMID 29145850, 2017). "In the present study, we investigated the prognostic utilities and most suitable cut-off values for Ki67 and PgR, and evaluated the relationship between Ki67 LI and PgR expression in ER-positive/HER2-negative breast cancer." (PMID 28532429, 2017). "MCF-7 cell is estrogen and progesterone receptor positive luminal A breast cancer cell line, but HER2 expression is weak in MCF-7 cell." (PMID 28915591, 2017). "TNBC is a highly aggressive and treatment-resistant breast cancer characterized by the absence/under-expression of three commonly targeted receptors: estrogen receptor (ER), progesterone receptor (PR) and human epidermal growth factor receptor II (HER2)." (PMID 28657611, 2017). "This is the first in-depth analysis of microRNAome profiles in PFC tissues of chemotherapy treated and untreated mouse TumorGraftTM models of triple negative and progesterone receptor positive breast cancer." (PMID 29179434, 2017). "Breast cancer can be divided into subtypes according to the expression of hormone receptors (HRs; estrogen receptor (ER) and progesterone receptor (PR)) and human epidermal growth factor receptor 2 (HER2)." (PMID 29371915, 2017). "One of the most aggressive and malignant types of breast cancer is the triple negative (estrogen receptor- (ER-), progesterone receptor- (PR-), human epidermal growth factor receptor 2- (HER2-)) basal-like adenocarcinoma." (PMID 29216863, 2017). "Tamoxifen is an antiestrogenic drug widely used in the treatment of estrogen receptor (ER)-and/or progesterone receptor (PR)-positive breast cancers." (PMID 29245979, 2017). "Estrogen via ER molecules stimulates proliferation of breast cancer cells and regulates the expression of other proteins in the tumor cells, including the progesterone receptor." (PMID 28356061, 2017). "Breast cancer is divided into several subtypes according to the estrogen receptor (ER), progesterone receptor (PgR), and HER2 status, which are indicators for therapeutic strategy." (PMID 29196757, 2017). "Triple negative breast cancer (TNBC), which comprises approximately 15% of all primary breast cancer diagnoses, lacks estrogen receptor alpha, progesterone receptor and human epidermal growth factor receptor 2 expression." (PMID 29228549, 2017). "The general subtyping of breast cancer in the clinic is based on the expression of three main types of receptor: estrogen receptor (ER), progesterone receptor (PR) and the human epidermal growth factor receptor 2 (HER2, also known as ErbB2)." (PMID 28583138, 2017).
breast cancer (continued). "We investigated the association between gamma-glutamyl transferase (GGT) and development of specific breast cancer subtypes based on oestrogen receptor (ER), progesterone receptor (PR) and HER2 status." (PMID 28264697, 2017). "In this study, we used high-throughput proteomics and microRNA profiling to characterize two subtypes of breast cancer with various prognoses: ER+/progesterone receptor-positive (PR+) HER2- breast cancer and triple-negative breast cancer (TNBC)." (PMID 28855612, 2017). "Nevertheless, the potential impact of here presented findings regarding PgR expression and Ki-67 values on patients’ management warrants a large prospective study of DFS and overall survival among breast cancer patients with various ER/PgR cancer phenotypes." (PMID 28356061, 2017). "For example, miR-423-5p recruits AGO2 to repress the transcription of progesterone receptor via inducing DNA methylation and H3K9me2 enrichment in breast cancer cells." (PMID 28827574, 2017). "Recent studies have shown that testing for progesterone receptor status helped doctors to choose the best treatment method and reduced breast cancer mortality." (PMID 29056033, 2017). "This is possibly related to the second report that among 398 patients early relapses in patients with Luminal B and HER2-negative breast cancers were related to PgR negativity." (PMID 28356061, 2017). "This antiserum will be applicable to clinicopathological examination of aromatase in addition to ER and PgR for an appropriate use of aromatase inhibitor on the treatment of breast cancer." (PMID 28489882, 2017). "Approximately 60-75% of patients with breast cancer are hormone receptor (HR)-positive at diagnosis, where HR refers to estrogen receptor (ER), progesterone receptor (PR), or both." (PMID 28881602, 2017). "Currently, the clinical management of breast cancer mainly relies on the molecular subtypes based on the expression of estrogen receptor, progesterone receptor and HER2 in primary tumors." (PMID 28337998, 2017). "Among these, luminal-type accounts for the most part of breast cancer and is characterized with the typical expression of estrogen receptor (ER) and/or progesterone receptor (PR), which can be effectively targeted with hormone therapy." (PMID 28438180, 2017). "The hormone receptors, estrogen receptor (ER) and progesterone receptor (PR), and human epidermal receptor 2 (HER2) serve as prognostic and diagnostic markers in breast cancer." (PMID 28388540, 2017). "In our study, 70% of breast cancers were positive for estrogen receptor and 67% were positive for progesterone receptor." (PMID 29201466, 2017). "Breast cancer can be classified depending on the status of estrogen receptor (ER) and/or progesterone receptor (PGR) and epidermal growth factor receptor 2 (ERBB2/HER2) in clinic." (PMID 28392805, 2017). "Here presented results suggest that the PgR expression on breast cancer cells is related to the Ki-67 value, here used as marker of tumor biology." (PMID 28356061, 2017). "The current research is essential to update the immunohistochemical activity of ER/PgR in primary breast cancers." (PMID 28173783, 2017). "The detection of the estrogen receptor (ER) and progesterone receptor (PgR) is crucial for prognostic evaluation and treatment choice of breast cancer for clinical practice." (PMID 28173783, 2017). "The positivity of the ER is generally more than 70% in women with breast cancer than that of PgR, 50%." (PMID 28173783, 2017). "A higher GPC/PCho ratio in triple negative compared to ER+/PgR+ breast cancer was observed, in concordance to the basal-like and luminal-like subtypes, respectively." (PMID 28509845, 2017). "In breast cancer, the level of AR expression is positively correlated with ER and/or PgR expression, and high AR expression is an indicator of good prognosis in HR-positive breast cancer." (PMID 28060723, 2017).
breast cancer (continued). "The presence of ER or PgR on breast cancer cells typically suggests slower-growing tumors, amenable to hormonal manipulation." (PMID 28356061, 2017). "The hormonal receptor status allows to distinguish four subgroups of breast cancers: ER+PgR+, ER+PgR-, ER-PgR+, and ER-PgR-." (PMID 28173783, 2017). "Approximately 80% of breast cancers express estrogen receptor (ER), progesterone receptor (PR), or both, and are therefore considered hormone receptor-positive (HR+)." (PMID 28725482, 2017). "A previous Tanzanian report showed that only 18% out of 60 studied cases of breast cancer were progesterone receptor positive." (PMID 29142588, 2017). "Clinical subtypes for breast cancer are based on the immunohistochemical (IHC) determination of estrogen receptor (ER), progesterone receptor (PR) and human epidermal growth factor receptor 2 (HER2)." (PMID 29212525, 2017). "The prevailing contemporary classification of breast tumors recognizes five basic immunohistochemical phenotypes: Luminal A, Luminal B1 and Luminal B2 are the three breast cancer types with positive ER or PgR expression." (PMID 28356061, 2017). "Steroid hormone receptors (HRs; i.e., estrogen receptor or progesterone receptor) are important prognostic and predictive factors for response to endocrine therapy in the treatment of breast cancer." (PMID 28544536, 2017). "Clinically, breast cancer is usually categorized based on the expression of specific receptors, including estrogen receptor (ER), progesterone receptor (PR), and human epidermal growth factor receptor 2 (HER2)/neu (also known as ERBB2)." (PMID 29108265, 2017). "There remains an urgent need for alternative, more robust, standardized, and precise assays with proven analytical and clinical validity for Ki67, HER2, ER, and PgR in routine breast cancer diagnostics." (PMID 28490348, 2017). "We used multivariable polychotomous unconditional logistic regression methods to conduct case-control comparisons among breast cancer subtypes defined by estrogen receptor, progesterone receptor, and human epidermal growth factor receptor-2 expression status." (PMID 28086982, 2017). "As a result, the mortality rate of patients with TNBC is significantly higher than among patients with other types of breast cancer (estrogen receptor α and progesterone receptor positive)." (PMID 29048370, 2017). "Expression of ESR1, PGR, HER2 and Ki67 is important for risk stratification and therapy in breast cancer." (PMID 28978063, 2017). "Progesterone receptor positivity was an important prognostic factor for survival in middle-aged women with breast cancer in this study." (PMID 29056033, 2017). "Consider the case of a column labeled “pr” in the breast cancer data referring to the status of the “progesterone receptor” in a breast tumor." (PMID 28437440, 2017). "Most breast cancers are hormone receptor–positive (HR+), with 75% to 83% of breast cancers expressing estrogen receptor (ER)-α and/or progesterone receptor." (PMID 28183331, 2017). "In our Institute in more than 90% of the early breast cancer patients, ER, PgR, HER2 and Ki-67 are evaluated on a core biopsy of the primary tumor before breast surgery and SLN biopsy." (PMID 28187209, 2017). "For premenopausal women with oestrogen receptor (ER)-positive or progesterone receptor (PgR)-positive breast cancer, the treatment strategies include ablative surgery, radiotherapy, cytotoxic chemotherapy, or adjuvant endocrine." (PMID 28415634, 2017). "Approximately 75% of breast cancers express typical genes of luminal epithelial cells, such as estrogen receptor (ER) and/or progesterone receptor (PR)." (PMID 28294120, 2017). "Further analysis of Caucasian patients with ER-positive breast cancer suggested that the patients with poor overall survival (Group 2) have significantly less progesterone receptor expression (odds ratio = 3.682, P < 0.0001)." (PMID 28487351, 2017).
breast cancer (continued). "Consistently, miR-9-5p and miR-9 3p were differentially expressed in the breast cancer subgroups identified by ER and PgR expression and HER2 amplification." (PMID 28345661, 2017). "Progesterone antagonists (antiprogestins) and progesterone receptor modulators (PRMs) are used in the treatment of PR+ breast cancer, and antagonism at the PR helps protect against breast cancer." (PMID 28685096, 2017). "Among 1522 patients with primary breast cancer ER+/PgR−/HER2- tumors showed poorer clinicopathologic characteristics compared with ER+/PgR+/HER2- tumors using a PgR threshold of 20% instead of 1%." (PMID 28356061, 2017). "Immunoreactivity of estrogen receptor (ER), progesterone receptor (PR) or Her2 in breast cancer tissue provides both predictive and prognostic information." (PMID 28427429, 2017). "TNBCs account for approximately 10 to 20% of all breast cancers and are characterized by the lack expression of estrogen receptor (ER), progesterone receptor (PR), and human epidermal growth factor receptor 2 (HER2)." (PMID 28054666, 2017). "Studies on different age, situ, locality, region and metastasis of breast cancer, estrogen receptor (ER) and progesterone receptor (PR) status are too limited to perform subgroup analysis." (PMID 28418881, 2017). "It has been known that the positive rate of ER and/or PgR in breast cancer is approximately 70%, and ER is considered to have key functions in the development and progression of breast cancer." (PMID 28532429, 2017). "The classification of breast cancer based on the molecular phenotype depends on the presence of the estrogen receptor (ER), the progesterone receptor (PR), and/or the type 2 human epidermal growth factor receptor (HER-2)." (PMID 29202842, 2017). "The molecular classification of breast cancer, based on the expression of estrogen receptor/progesterone receptor (ER/PR) and epidermal growth factor receptor 2 (HER2), provided different prognostic/predictive implications and therapeutic information." (PMID 28422733, 2017). "In breast cancer (BC), androgen receptor (AR) expression is related to estrogen receptor (ER) and/or progesterone receptor (PgR) expression." (PMID 28060723, 2017). "Tamoxifen is a selective estrogen receptor modulator used for adjuvant treatment of luminal (estrogen receptor (ER)-positive and/or progesterone receptor (PR)-positive) breast cancer (BC) subtypes." (PMID 29183390, 2017). "Hazard ratio for breast cancer-specific mortality was 0.44 (95 % CI 0.27–0.71, p = 0.001) for ER+/PgR+ patients and 0.65 (95 % CI 0.35–1.21, p = 0.17) for ER+/PgR− patients." (PMID 27722840, 2016). "On the other hand, breast cancer is a complex disease that is mainly grouped based on its hormone receptor subtype (estrogen receptor or progesterone receptor positivity) and amplification of the ERBB2 gene." (PMID 27754415, 2016). "A correlation was found between patients strongly expressing CHIP and ER‐positive and/or PgR‐positive breast cancer." (PMID 27334118, 2016). "There are three important markers for breast cancer: the estrogen receptor (ER), the progesterone receptor (PR), and Human epidermal growth factor receptor (HER2/neu)." (PMID 27542274, 2016). "Luminal A/B breast cancers typically express the estrogen receptor (ER) and progesterone receptor (PR), while Her2-like are typically characterized by overexpression of the human epidermal growth factor receptor (ERBB2, Her2/neu)." (PMID 27286452, 2016). "Reporter assays using isolated regulatory sequences of the PGR gene have implicated both classical and tethering mechanism in the transcriptional activation of PGR in MCF7 breast cancer cells." (PMID 27007157, 2016).
breast cancer (continued). "The majority of the patients in this study had stage 1 breast cancer and was ER-positive and PgR-positive, which was consistent with the statistical data in Japan." (PMID 27064454, 2016). "Chemotherapeutic options for breast cancers depend on the expressions of estrogen receptor (ER) and progesterone receptor (PR), and on the amplification of human epidermal growth factor receptor 2 (HER-2/Neu)." (PMID 27871326, 2016). "The significance of PgR has also been demonstrated in metastatic ER+ breast cancer, where increased levels of PgR improved the response rate to tamoxifen." (PMID 27722840, 2016). "Breast cancer subtypes were defined by the expression status of estrogen receptor (ER), progesterone receptor (PR), and human epidermal growth factor receptor 2 (HER2)." (PMID 27317095, 2016). "We suggest that IHC determined tumor content of both ER and PgR should be taken into consideration when breast cancer patients receive postoperative advice." (PMID 27722840, 2016). "In other words, breast cancer exhibits various aspects depending on the estrogen receptor (ER) or progesterone receptor (PR) status and menopausal status." (PMID 27283141, 2016). "In fact, in the RETROHER study, we found little benefit of adjuvant trastuzumab in 163 women with HER2-positive operable breast cancer whose tumors were positive for both the ER and PgR in ≥50% of tumor cells." (PMID 26910921, 2016). "Until now only estrogen receptor (ESR1) and progesterone receptor (PGR) have been routinely assessed as hormone receptors in human breast cancer due to their prognostic and predictive value in human mammary carcinoma therapy." (PMID 27649560, 2016). "NZ produced a significant chemosensitization in breast cancer cell lines that differ for the expression of estrogen receptor, progesterone receptor and human epidermal growth factor receptor 2 (Her2)." (PMID 26980746, 2016). "Breast cancers can be divided into several subtypes, mainly based on expression of oestrogen receptor (ER), progesterone receptor (PR) and human epidermal growth factor receptor 2 (HER2)." (PMID 27725631, 2016). "Luminal B breast cancers are characterized by a lower expression of estrogen receptor (ER), a low expression of progesterone receptor (PgR) and a high histologic grade." (PMID 27542253, 2016). "The three clinically most-useful receptors in breast cancer cells, because they dictate therapy, are the estrogen receptor (ER), progesterone receptor (PR), and human epidermal growth factor receptor 2 (HER2)." (PMID 27853751, 2016). "Approximately two-thirds of patients diagnosed with breast cancer have hormone-receptor–positive [estrogen receptor (ER) and/or progesterone receptor (PgR)] tumors and are suitable candidates for endocrine therapy." (PMID 26350351, 2016). "In luminal B-like breast cancers, for example, low progesterone receptor expression and high Ki-67 index are suggested predictors of greater aggressiveness." (PMID 27798667, 2016). "Breast cancers with high levels of CACNA1H (Cav3.2) (2nd, 3rd, 4th quartile) showed a significant elevation in levels of ESR1 and PGR compared to breast cancers with significantly low levels of Cav3.2 (1st quartile)." (PMID 27034617, 2016). "We next analyzed the correlation between DACT2 methylation and clinicopathological features of breast cancer patients, including age, tumor size, tumor grade, lymph node metastasis, and estrogen receptor (ER), progesterone receptor (PR) and HER2 status." (PMID 27708215, 2016). "Retrospective evaluation of oestrogen receptors (ER) and progesterone receptors (PgR) in 732 patients from the original study showed that tamoxifen reduced subsequent breast cancer events by 51% for women with ER-positive DCIS." (PMID 26686313, 2016). "The results of a histological examination for a core needle biopsy specimen were a breast cancer (invasive ductal carcinoma) with an immunohistochemical status of ER (+), progesterone receptor (PgR) (+), HER2 (3+), and Ki67 40 %." (PMID 27683008, 2016).